BCKDK (branched chain keto acid dehydrogenase kinase)
Description:
Serine/threonine-protein kinase component of macronutrients metabolism. Forms a functional kinase and phosphatase pair with PPM1K, serving as a metabolic regulatory node that coordinates branched-chain amino acids (BCAAs) with glucose and lipid metabolism via two distinct phosphoprotein targets: mitochondrial BCKDHA subunit of the branched-chain alpha-ketoacid dehydrogenase (BCKDH) complex and cytosolic ACLY, a lipogenic enzyme of Krebs cycle. Phosphorylates and inactivates mitochondrial BCKDH complex a multisubunit complex consisting of three multimeric components each involved in different steps of BCAA catabolism: E1 composed of BCKDHA and BCKDHB, E2 core composed of DBT monomers, and E3 composed of DLD monomers. Associates with the E2 component of BCKDH complex and phosphorylates BCKDHA on Ser-337, leading to conformational changes that interrupt substrate channeling between E1 and E2 and inactivates the BCKDH complex. Phosphorylates ACLY on Ser-455 in response to changes in cellular carbohydrate abundance such as occurs during fasting to feeding metabolic transition. Refeeding stimulates MLXIPL/ChREBP transcription factor, leading to increased BCKDK to PPM1K expression ratio, phosphorylation and activation of ACLY that ultimately results in the generation of malonyl-CoA and oxaloacetate immediate substrates of de novo lipogenesis and glucogenesis, respectively. Recognizes phosphosites having SxxE/D canonical motif.
Synonyms: BDK; BCKDKD
Tractability: Small molecule: a structure with a bound ligand is known. PROTAC: it is named in the literature on targeted protein degradation; ubiquitination databases record sites on it; its protein half-life has been measured.
Target class: Enzyme; Transferase
Gene: Protein-coding gene on chromosome 16 (31,106,107 to 31,112,791, forward strand). Ensembl gene ENSG00000103507.
Subcellular location: Mitochondrion matrix
Subcellular location (Human Protein Atlas): Mitochondria
Pathways (Reactome):
Disease: Branched-chain ketoacid dehydrogenase kinase deficiency
Metabolism: Branched-chain amino acid catabolism
Gene Ontology:
Molecular function: [3-methyl-2-oxobutanoate dehydrogenase (acetyl-transferring)] kinase activity; protein binding; protein serine kinase activity; protein serine/threonine phosphatase activity; ATP binding; kinase activity; protein serine/threonine kinase activity; catalytic activity, acting on a protein; protein kinase activity; transferase activity, transferring phosphorus-containing groups
Biological process: lipid biosynthetic process; amino acid catabolic process; branched-chain amino acid catabolic process; regulation of glucose metabolic process; regulation of pyruvate decarboxylation to acetyl-CoA; L-isoleucine catabolic process; L-leucine catabolic process; L-valine catabolic process; negative regulation of amino acid metabolic process; spermatogenesis
Cellular component: mitochondrion; mitochondrial matrix; oxoglutarate dehydrogenase complex
Genetic constraint (gnomAD): Loss-of-function variants: 28 observed, 44.89 expected, observed/expected ratio (o/e) 0.62, 90% interval 0.46 to 0.86. The upper end of that interval is the gene's LOEUF score, 0.86, which puts it in group 3 of 6, group 1 being the genes least tolerant of losing a copy. Missense variants: 483 observed, 599.85 expected, observed/expected ratio (o/e) 0.81, 90% interval 0.75 to 0.87. Synonymous variants: 257 observed, 239.85 expected, observed/expected ratio (o/e) 1.07, 90% interval 0.97 to 1.19.
Gene-disease validity (ClinGen):
ClinGen rates the evidence that BCKDK causes each of these diseases.
branched-chain keto acid dehydrogenase kinase deficiency (autosomal recessive): Definitive. A rare disorder of branched-chain amino acid metabolism characterized by childhood-onset epilepsy, autism and intellectual disability with reduced levels of plasma branched chain aminoacids.
Homologues: Orthologues: chimpanzee BCKDK (99% identical), macaque BCKDK (98% identical), rabbit BCKDK (97% identical), dog BCKDK (96% identical), rat Bckdk (96% identical), mouse Bckdk (95% identical), guinea pig BCKDK (95% identical), tropical clawed frog bckdk (80% identical), pig BCKDK (78% identical), zebrafish bckdk (76% identical). Paralogues in human: PDK1 (31% identical), PDK2 (29% identical), PDK3 (28% identical), PDK4 (27% identical).
Diseases named in the same sentence as BCKDK in open-access papers:
BCKDK is named in the same sentence as 73 diseases in open-access papers, as found by Europe PMC text mining. Sharing a sentence is not in itself a finding about the gene and the disease. The quoted sentences say what the papers report.
colorectal cancer (14 papers, 2020 to 2025). A primary or metastatic malignant neoplasm that affects the colon or rectum. "Another study documented that increased BCKDK expression was associated with metastasis in colorectal cancer." (PMID 35812393, 2022). "In patients with colorectal cancer, high BCKDK expression is associated with poor prognosis." (PMID 38054015, 2023). "Since BCKDK is closely associated with tumor migration in colorectal cancer, we investigated whether BCKDK also regulated OC migration." (PMID 35498541, 2022). "It was shown that higher BCKDK expression was associated with shorter survival in colorectal cancer, and BCKDK could promote tumorigenesis in vivo and ex vivo through the mitogen-activated protein kinase (MAPK) signaling pathway." (PMID 35812393, 2022). "High expression of BCKDK and certain malignant proliferation behaviors have been confirmed in colorectal cancer, breast cancer, and NSCLC." (PMID 40438606, 2025). "BCKDK reportedly promotes the tumorigenesis of colorectal cancer by upregulating the mitogen-activated protein kinase (MEK)-extracellular signal-regulated kinase (ERK) signaling pathway." (PMID 39795113, 2024). "Elevated expression of BCKDK correlates with a poor prognosis for several cancers, such as breast cancer, colorectal cancer, and non-small lung cancer." (PMID 39795113, 2024). "Nonreceptor tyrosine kinase Src appears to enhance the activity and stability of BCKDK through phosphorylation at tyrosine 246, which promotes the migration, invasion, and epithelial-mesenchymal transition of colorectal cancer cells." (PMID 39795113, 2024). "Preclinical studies on colorectal cancer demonstrated that BCKDK activates MEK/ERK pathway, inducing tumorigenesis." (PMID 37637065, 2023). "Previous studies have reported that BCKDK promotes epithelial-to-mesenchymal transition (EMT) in colorectal cancer, which is related to the promotion of cancer cell adhesion and its motility." (PMID 37460470, 2023). "A significant upregulation of BCKDK was reported in patients with colorectal cancer and was accompanied by an unpromising prognosis." (PMID 37637065, 2023). "In agreement with our previous study, which demonstrated that BCKDK promoted colorectal cancer proliferation by targeting the MEK1." (PMID 35498541, 2022). "BCKDK promotes carcinogenesis in colorectal cancer and hepatocellular carcinoma, and the MAPK signaling pathway functions in this process." (PMID 35498541, 2022). "Branched-chain amino acid metabolism promotes EMT and metastasis in colorectal cancer through its counterpart enzyme, branched-chain α-ketoacid dehydrogenase kinase (BCKDK)." (PMID 35736645, 2022). "BCKDK promoted colorectal cancer and hepatocellular carcinoma metastasis and proliferation via the ERK signaling pathway." (PMID 35498541, 2022). "A rate-limiting enzyme in BCAA catabolism, named BCKDK, has also been reported to promote colorectal cancer tumorigenesis via upregulating the MAPK pathway by phosphorylating MEK at Ser221." (PMID 34568427, 2021). "Branched-chain α-keto acid dehydrogenase kinase (BCKDK), the key enzyme of branched-chain amino acids (BCAAs) metabolism, has been reported to promote colorectal cancer (CRC) tumorigenesis by upregulating the MEK-ERK signaling pathway." (PMID 32238881, 2020). "The online analysis showed that the mRNA level of BCKDK was significantly higher in colorectal carcinoma (n = 70, ***p < 0.001) and rectal adenocarcinoma (n = 65, ***p < 0.001) than in corresponding normal tissues." (PMID 32238881, 2020). "A previous study reported that BCKDK could be phosphorylated by Src, thereby promoting metastasis of colorectal cancer." (PMID 39025830, 2024). "We previously confirmed that BCKDK interacted with MEK in colorectal cancer cells." (PMID 35498541, 2022). "Notably, stabilizing BCKDK via Src promoted migration, invasion, and metastasis in colorectal cancers." (PMID 34526485, 2021). "BCKDK may serve as a novel therapeutic target for colorectal cancer." (PMID 40438606, 2025).
colorectal cancer (continued). "Additionally, studies have shown that BCKDK enhances the MAPK signaling pathway by directly phosphorylating MEK, rather than through branched-chain amino acid catabolism, thereby promoting colorectal cancer progression." (PMID 40438606, 2025). "Moreover, the enhanced activity of branched-chain α-keto acid dehydrogenase kinase (BCKDK), the key enzyme of BCAAs metabolism, was shown to promote migration, invasion and EMT of colorectal cancer." (PMID 34921655, 2022). "First, we detected the endogenous expression of BCKDK in seven CRC cell lines, and BCKDK was knocked down in HCT116 metastatic colorectal carcinoma and SW620 colorectal adenocarcinoma cell lines, which showed high BCKDK expression." (PMID 32238881, 2020).
heart failure (11 papers, 2020 to 2025). Inability of the heart to pump blood at an adequate rate to meet tissue metabolic requirements. "The BCKDK gene codifies a branched-chain ketoacid dehydrogenase kinase, which participates in lipid metabolism, and its mutation has been associated with nonalcoholic fatty liver disease, cancer, PD, heart failure, neurodevelopmental disorders, and other conditions." (PMID 40722297, 2025). "Cardiac-specific loss of BCKDK does not reproduce the protective effects in either hemodynamic models or ischemic models of heart failure." (PMID 38301896, 2024). "Cardiac-specific loss of BCKDK does not reproduce the protective effects in either hemodynamic or ischemic models of heart failure." (PMID 37645724, 2023). "Indeed, PPM1K knockout exacerbates while inhibition of BCKDK interaction with BCKDH confers potent amelioration to pressure-overload induced heart failure, highlighting the potential of PPM targeted manipulation as a viable therapeutic strategy for heart failure." (PMID 34091011, 2021). "BCKDK inhibitors with greater potency than BT2 have been recently developed and evaluated in preclinical models of heart failure and diet-induced obesity." (PMID 38301896, 2024). "Previous studies have shown that 3,6-dichlorobenzo[b] thiophene-2-carboxylic acid (BT2) promotes BCAA degradation by inhibiting BCKDK, increasing the activity of BCKDH and effectively alleviating stress-induced heart failure." (PMID 37149696, 2023). "It has been proposed that enhancing BCAA catabolism through the pharmacological inhibition of BCKDK could mitigate BCAA accumulation, thereby ameliorating heart failure pathophysiology." (PMID 39195229, 2024). "Alterations of branched-chain amino acid metabolism have been described in relation to heart failure, however, there is no evident link between BCKDK and CHD." (PMID 33110418, 2020). "While the results could suggest that whole-body BCKDK inhibition cannot be reproduced by Bckdk ablation in individual tissues, they perhaps also suggest an alternative mechanism by which BT2 confers protection from heart failure and metabolic disease distinct from BCAA oxidation." (PMID 37645724, 2023).
epilepsy (10 papers, 2016 to 2025). A brain disorder characterized by episodes of abnormally increased neuronal discharge resulting in transient episodes of sensory or motor neurological dysfunction, or psychic dysfunction. "Loss of BCKDK function results in neurological abnormalities in mice and in a potentially treatable form of autism with epilepsy in humans." (PMID 27472223, 2016). "In a similar vein, WES of consanguineous families with ASD, ID and epilepsy led to the identification of mutations in the gene BCKDK (Branched Chain Ketoacid Dehydrogenase Kinase), encoding an enzyme regulating the catabolism of the branched-chain amino acids (BCAAs)." (PMID 30089840, 2018). "Epilepsy-associated genes (TPP1, BCKDK, ALG3, and PACS1) were upregulated and enriched in PZ and showed higher expression in the TLE as compared with the healthy control scRNA data." (PMID 39541170, 2025). "Issues with the BCKDK (Branched Chain Ketoacid Dehydrogenase Kinase) gene for example, have been discussed in the context of autism, intellectual (learning) disability and epilepsy appearing together." (PMID 33995134, 2021). "Recent studies show that loss-of-function mutations in BCKDK leading to excess rather than restricted BCAA oxidation may lead to autism spectrum disorder with epilepsy in humans." (PMID 35205278, 2022). "Also, many diseases are related to the alteration of the BCAA catabolism enzyme branched-chain α-keto acid dehydrogenase kinase (BCKDK), including maple syrup urine disease, human autism with epilepsy, and so on." (PMID 35923208, 2022).
autism (9 papers, 2016 to 2025). Persistent deficits in social interaction and communication and interaction as well as a markedly restricted repertoire of activity and interest as well as repetitive patterns of behavior. "Furthermore, pathogenic variants in branched-chain ketoacid dehydrogenase kinase (BCKDK) lead to autism." (PMID 33050626, 2020).
Obesity (9 papers, 2019 to 2024). Accumulation of substantial excess body fat. "Association of hepatic BCKDK mRNA expression with features of NASH in people with severe obesity." (PMID 35797133, 2022). "This phenomenon can be reversed by BCAA diet restriction or regulating the BCKDK/PPM1K ratio in mouse models of obesity and insulin resistance." (PMID 37699892, 2023). "Hepatic BCKDK levels are elevated in genetic models of obesity and following ingestion of diets high in fructose in rats, whereas PPM1K levels are low in these settings and increased during fasting." (PMID 35797133, 2022). "BCKDK mRNA expression, remained unaltered in the class I obese patients, decreased in class II obesity and increased in the class III obese group (when compared to the pre-obese patients)." (PMID 32903728, 2020). "Moreover, we demonstrated that the hepatic expression of BCKDK mRNA is strongly associated with steatosis grade, ballooning, and NASH in livers of 2 distinct bariatric surgery populations with severe obesity." (PMID 35797133, 2022). "In addition, obesity could inhibit hepatic utilization of BCAAs and cause the inactivation of BCKDH by increasing the ratio of BCKDK (BCKDH kinase)/PPM1K (BCKDH dephosphorylase) in hepatocytes." (PMID 37699892, 2023). "Thus, increased levels of BCAA in plasma from subjects with obesity are likely to be the result of reduced expression of BCAT or decreased BCKD activity via either increased expression of BCKDK or suppression of PPM1K." (PMID 36771236, 2023). "In livers of HCC patients, and animal models, including high-fat diet-induced obesity and HCC tumor models, BCKDH activity and expression were found to be downregulated, and BCKDH kinase (BCKDK), the enzyme responsible for suppressing the activity of BCKDH, was found to be upregulated." (PMID 35740464, 2022). "However, in the SAT of patients with class II and class III obesity, mRNA and protein levels of BCAA catabolic enzymes were markedly downregulated along with increased levels of pBCKDE1α and BCKDK." (PMID 32903728, 2020). "In light of our observation of a strong association of circulating BCKA and hepatic BCKDK expression with NAFLD/NASH in people with severe obesity we aimed to determine whether another major lipogenic transcription factor, SREBP1 might also regulate hepatic BCKDK gene expression." (PMID 35797133, 2022). "Although they also showed that BCKDK inhibitor can increase BCKD activity, reduce plasma levels of BCAAs and BCKAs, and improve insulin sensitivity in DIO mice, this intervention did not reduce obesity." (PMID 35448521, 2022).
maple syrup urine disease (8 papers, 2018 to 2025). An autosomal recessive inherited disorder caused by mutations in the BCKDHA, BCKDHB, DBT, and DLD genes. "We identified, by whole exome-sequencing analysis, the p.His162Gln variant of the BCKDK gene in a neonate, picked up by newborn screening, with a biochemical phenotype of a mild form of maple syrup urine disease (MSUD)." (PMID 35205278, 2022). "Dysfunction of BCKDK is closely related to various human diseases, especially maple syrup urine disease." (PMID 35498541, 2022). "All these data underscore the critical role of BCAAs metabolism in humans' health and disease, as was evidenced with the characterization of maple syrup urine disease (MSUD) and, more recently, with the description of branched-chain ketoacid dehydrogenase kinase (BCKDK) deficiency." (PMID 29743968, 2018). "BCKDK exerts a vital role in many serious diseases such as DR, maple syrup urine disease (MSUD), and obesity." (PMID 37432261, 2023).